TRAF3IP2 (TRAF3 interacting protein 2)
Diseases named in the same sentence as TRAF3IP2 in open-access papers (continued):
Sharing a sentence is not in itself a finding about the gene and the disease.
glioblastoma (6 papers, 2018 to 2025). The most malignant astrocytic tumor (WHO grade IV). "In glioblastoma, we reported that silencing TRAF3IP2 is linked to reduced tumor growth and metastasis." (PMID 32483202, 2020). "As a proof-of-concept, we used the flank xenograft model to study the causal role of TRAF3IP2 and its potential as a therapeutic target in glioblastoma." (PMID 30038719, 2018). "The study aimed to investigate the causal role of TRAF3IP2 in glioblastoma pathology." (PMID 30038719, 2018). "The results showed a marked increase in TRAF3IP2 expression in all 10 cases of glioblastoma tumors, compared to low or undetectable levels in adjacent normal brain tissue (n = 11), indicating that glioblastoma tumors express high levels of TRAF3IP2." (PMID 30038719, 2018). "Our data identify TRAF3IP2 as a potential therapeutic target in glioblastoma growth and dissemination." (PMID 30038719, 2018). "Expression levels of Cyclin-Dependent Kinase (CDK-1, CDK-2, and CDK-6) were also significantly down-regulated in U87TRAF3IP2KD cells (-9.3, -2.4, and -2.1, respectively), indicating that silencing TRAF3IP2 affects glioblastoma cell cycle progression." (PMID 30038719, 2018). "Our in vitro data demonstrate that similar to primary glioblastoma tumor tissues, malignant glioblastoma cell lines (U87 and U118) express high levels of TRAF3IP2." (PMID 30038719, 2018). "Concertedly, these in vitro and in vivo data identify TRAF3IP2 as a novel and a potential therapeutic target in glioblastoma." (PMID 30038719, 2018). "Our data show that silencing TRAF3IP2 significantly increased its expression in U87 glioblastoma cells, possibly contributing to reduced tumor growth in the flank xenograft model." (PMID 30038719, 2018). "In this study, we have shown that TRAF3IP2 is overexpressed in malignant U87 glioblastoma cells, and its silencing inhibits both basal and inducible NF-κB activation." (PMID 30038719, 2018). "Our future studies will determine the causal role of TRAF3IP2 in the pathogenesis of glioblastoma using the brain PDX (patient-derived xenograft) model, which is the host tissue for glioblastoma." (PMID 30038719, 2018). "To investigate the role of TRAF3IP2 in the tumorigenicity of malignant U87 glioblastoma cells, we injected TRAF3IP2-silenced U87 cells (U87TRAF3IP2KD cells) into the flank region of immunodeficient NIH-III mice and followed for up to 60 days." (PMID 30038719, 2018). "Our data also show for the first time that silencing TRAF3IP2 inhibits the spheroid forming ability of malignant glioblastoma cell lines U87 and U118." (PMID 30038719, 2018). "Treating existing tumors formed by the wild type U87 glioblastoma cells with TRAF3IP2 shRNA significantly reduces tumor size in the flank xenograft model." (PMID 30038719, 2018). "Similar to glioblastoma tumors, the malignant U87 and U118 cells also expressed high levels of TRAF3IP2 mRNA (versus SVG p12 cells; 69.8%, P<0.01)." (PMID 30038719, 2018). "Supporting these observations, the human malignant glioblastoma cell lines U87 and U118 also expressed high levels of TRAF3IP2, justifying the use of these cell lines in the current study." (PMID 30038719, 2018). "Our data show that silencing TRAF3IP2 down regulates TOP2A expression by a significant ∼7.5-fold in the malignant U87 glioblastoma cell line." (PMID 30038719, 2018). "Together, these novel data indicate that TRAF3IP2 is a master regulator of malignant signaling in glioblastoma, and its targeting modulates the TME and inhibits tumor growth by suppressing the expression of mediators involved in inflammation, angiogenesis, growth, and malignant transformation." (PMID 30038719, 2018). "Our data show that silencing TRAF3IP2 significantly inhibits its expression in glioblastoma cells." (PMID 30038719, 2018).
glioblastoma (continued). "Having demonstrated that TRAF3IP2-silenced malignant U87 glioblastoma cells form significantly smaller tumors, we next determined whether treating existing tumors by lentiviral TRAF3IP2 shRNA regresses their size." (PMID 30038719, 2018). "Our data showed high levels of TRAF3IP2 expression in primary human glioblastoma tumors." (PMID 30038719, 2018). "In order to demonstrate the clinical relevance of TRAF3IP2 in glioblastoma, we analyzed its expression by IHC using a commercially available brain glioblastoma tissue array that contains tissue sections from 10 different glioblastoma patients of both genders and different ages." (PMID 30038719, 2018). "Further, TRAF3IP2-silenced cells showed a significant increase in the number of cells in G0/G1 phase (P < 0.001) and a marked decrease in S and G2 phases (P < 0.05), indicating that silencing TRAF3IP2 inhibits proliferation of malignant U87 glioblastoma cells." (PMID 30038719, 2018). "Our novel data show that silencing TRAF3IP2 inhibits the spheroid-forming ability of malignant glioblastoma cell lines, indicating that targeting TRAF3IP2 not only inhibits the proliferative potential of tumor cells, but also the growth of CSCs, ultimately eliminating the tumor and its recurrence." (PMID 30038719, 2018). "These proof-of-principal studies using human malignant glioblastoma cell lines show the crucial role of TRAF3IP2 in GBM pathology." (PMID 30038719, 2018). "Interestingly, several gene products that are being targeted in ongoing clinical trials are TRAF3IP2-responsive genes, indicating that TRAF3IP2 could be a potential and promising therapeutic target in glioblastoma, a fatal disease." (PMID 30038719, 2018). "Therefore, we investigated whether silencing TRAF3IP2 affects the sphere-forming ability of glioblastoma cells." (PMID 30038719, 2018). "Previously, we showed the role of TRAF3IP2 in TNBC and glioblastoma tumorigenesis, and showed that the inhibition of TRAF3IP2 prevents tumor growth and cancer cell proliferation in vitro and in vivo." (PMID 41436543, 2025). "Another novel finding of our study is that silencing TRAF3IP2 inhibits the expression of both SERPINB4 and SERPIN2 in the U87 glioblastoma cell line." (PMID 30038719, 2018). "Importantly, silencing TRAF3IP2 made the TME less inflammatory and tumorigenic, revealing its crucial role in pro-inflammatory and pro-tumorigenic TME in glioblastoma." (PMID 30038719, 2018). "However, the spheroids formed by TRAF3IP2-silenced U87 cells (U87TRAF3IP2KDversus U87control shRNA cells) expressed markedly reduced VEGF, IL-17R, IL-1β, IL-6, and IL-8 expression, further demonstrating a pro-angiogenic and pro-inflammatory role of TRAF3IP2 in glioblastoma cells." (PMID 30038719, 2018).
lupus (6 papers, 2015 to 2022). "In our previous works, we described associations between SNPs in the STAT4, IL10, TRAF3IP2, and HCP5 (HLA complex P5) genes and systemic lupus erythematosus (SLE) susceptibility." (PMID 30882006, 2019).
Autoimmunity (3 papers, 2014 to 2021). The occurrence of an immune reaction against the organism's own cells or tissues. "TRAF3IP2 is another member of the TRAF family and encodes Act1 protein, which binds to TRAF5 thereby playing an important role in controlling inflammatory responses and autoimmunity through its effect on CD40L and IL-17 signaling." (PMID 24416204, 2014).
candidiasis (3 papers, 2021 to 2025). Infection with the organism Candida. "Candidiasis often occurs in individuals with an inherited (gene mutations RORγ, RORγt, STAT3, TRAF3IP2, IL-17F, IL-17RA, IL-17RC) or acquired (drug-induced) dysregulation of IL-17." (PMID 40863217, 2025).
glioma (3 papers, 2018 to 2022). A benign or malignant brain and spinal cord tumor that arises from glial cells (astrocytes, oligodendrocytes, ependymal cells). "Among the cell adhesion molecules, silencing TRAF3IP2 reduced ITGAV (Integrin-αV) expression which is known to be involved in the migration of glioma cells and is thus considered to contribute to invasiveness." (PMID 36046049, 2022). "Several reports have demonstrated that TRAF3IP2 is an upstream regulator of NF-κB activation in various cell types, including glioma cells." (PMID 30038719, 2018).
Sjögren’s syndrome (3 papers, 2019 to 2021). "The Act1 (TRAF3IP2 or CIKS) knockout mouse is a model for SLE and Sjogren’s syndrome." (PMID 31978964, 2020).
atherosclerosis (2 papers, 2024 to 2025). A disease characterized by the build-up of fatty material and calcium deposition in the arterial wall resulting in partial or complete occlusion of the arterial lumen. "Sex (OR 0.446 [0.230–0.863], p=0.017), diabetes history (OR 2.099 [1.131–3.896], p=0.019), phosphoremia (OR 0.252 [0.065–0.972], p=0.045) and TRAF3IP2 (OR 1.040 [1.004–1.076], p=0.027) were independent risk factors for atherosclerosis." (PMID 41189624, 2025). "LASSO and multivariate logistic regression analyses revealed that sex, diabetes history, phosphoremia status and TRAF3IP2 expression were independent risk factors for atherosclerosis." (PMID 41189624, 2025). "The results revealed that sex, diabetes history, phosphoremia and TRAF3IP2 expression (OR 1.040 [1.004–1.076], p=0.027) were independent risk factors for atherosclerosis." (PMID 41189624, 2025). "Notably, the results of this study indicated that higher levels of TRAF3IP2 and lower phosphoremia level were important risk factors for the development of atherosclerosis." (PMID 41189624, 2025). "Differentially expressed genes (DEGs), functional enrichment and protein–protein interaction network analyses were performed to determine the function of TRAF3IP2 in atherosclerosis." (PMID 41189624, 2025). "Using multiple network databases, we conducted a molecular characteristic analysis to assess the potential function of TRAF3IP2 in the diagnosis and prognosis of atherosclerosis." (PMID 41189624, 2025). "The findings of this study indicate that TRAF3IP2 can function as a biomarker of atherosclerosis." (PMID 41189624, 2025). "Evidence has shown that TRAF3IP2 plays an important role in the process of atherosclerosis." (PMID 41189624, 2025). "Moreover, TRAF3IP2 is involved in the cellular response to inflammation, which is a basic process of atherosclerosis." (PMID 41189624, 2025). "A positive correlation has been identified between TRAF3IP2 levels and CADi, suggesting that TRAF3IP2 may play a role in the development of atherosclerosis." (PMID 41189624, 2025). "Therefore, TRAF3IP2 and RECK could serve as effective therapeutic targets in atherosclerosis development and progression." (PMID 39451191, 2024).
cervical cancer (2 papers, 2014 to 2024). A primary or metastatic malignant neoplasm involving the cervix. "Of note, PPARG exon 6 and TRAF3IP2 exon 2 specifically overlap AP-1 ChIP-seq peaks in human cervical cancer cells (HeLa) cells." (PMID 25340400, 2014).
diabetes (2 papers, 2021 to 2025). "In this study, we screened and identified four CAD-associated independent risk factors, including sex, diabetes history, phosphoremia, and TRAF3IP2." (PMID 41189624, 2025). "A nomogram composed of sex, diabetes history, phosphoremia, and TRAF3IP2 expression may predict the risk of CAD." (PMID 41189624, 2025). "By using the least absolute shrinkage and selection operator (LASSO) regression model, we identified 9 risk factors, namely, age, sex, smoking history, diabetes history, serum creatinine level, phosphoremia, total cholesterol (TC) level, triglyceride (TG) level, and TRAF3IP2 expression." (PMID 41189624, 2025). "Therefore, our present study sets the stage for the development of βFaar, TRAF3IP2, and potentially other βFaar interacting molecules as therapeutic targets for obesity-associated diabetes and other obesity-associated diseases." (PMID 34183666, 2021).
eczema (2 papers, 2017 to 2019). "During the cross-check on atopy-related mutations in PID genes, TRAF3IP2 was identified of which mutations were described that might result in an eczema phenotype." (PMID 31333817, 2019).
mental disorder (2 papers, 2022 to 2023). A disease that has its basis in the disruption of mental process. "As the anti-sense sibling of TRAF3IP2, TRAF3IP2-AS1 was initially recognized in non-tumor pathological conditions, such as cocaine abuse, mental disorders and auto-immune disease." (PMID 36992083, 2023).
Myocardial fibrosis (2 papers, 2017 to 2022). "The causal role of IL-17, which signals exclusively via TRAF3IP2, is well recognized in myocardial fibrosis and DD." (PMID 28476142, 2017).
osteoporosis (2 papers, 2020 to 2021). A condition of reduced bone mass, with decreased cortical thickness and a decrease in the number and size of the trabeculae of cancellous bone (but normal chemical composition), resulting in increased fracture incidence. "In addition, the study of these molecules SNTG2, TRAF3IP2, and ITGA6 can be tested as therapeutic targets in osteoporosis‐related VF." (PMID 32602654, 2020).
pericarditis (2 papers, 2015 to 2025). An inflammatory process affecting the pericardium. "A binary logistic regression analysis demonstrated that both TRAF3IP2 rs33980500 and anti-La/SSB could be independently associated with the development of pericarditis (P = 0.006 and P = 0.032, resp)." (PMID 26798662, 2015).
schizophrenia (2 papers, 2019 to 2022). A major psychotic disorder characterized by abnormalities in the perception or expression of reality. "Interestingly, that the top H3K4me3 marked loci are also reported in top of genetic loci associated with schizophrenia (HLA locus on chromosome 6 and TRAF3IP2 locus on chromosome 22) suggesting a potential causative role for such epigenetic changes." (PMID 31624234, 2019).
Alzheimer disease (1 paper, 2025). A progressive, neurodegenerative disease characterized by loss of function and death of nerve cells in several areas of the brain leading to loss of cognitive function such as memory and language. "TRAF3 interacting protein 2 (TRAF3IP2) is reported to have participated in the progression of Alzheimer's disease, a neurodegenerative condition." (PMID 41189279, 2025).
Behçet's disease (1 paper, 2014). "Three SNPs (rs6540679, rs12569232, rs10863888) of TRAF5 and rs13210247 of TRAF3IP2 were significantly associated with Behçet's disease and VKH syndrome (corrected P values ranging from 9.45×10−12 to 0.027)." (PMID 24416204, 2014).
brucellosis (1 paper, 2021). Brucellosis is a bacterial infection that spreads from animals to people via unpasteurized dairy products or by exposure to contaminated animal products or infected animals. "We investigated the expression of IL-25, IL-17RB, Th2-LCR lncRNA, and TRAF3IP2, which play roles in brucellosis." (PMID 35071039, 2021). "Thus, this work focused on the expression of four Th2 and Th17 immunity-related factors (Th2-LCR lncRNA, IL-25, TRAF3IP2, and IL-17RB) in different stages of brucellosis." (PMID 35071039, 2021). "TRAF3IP2 might represent an interesting candidate as a potent marker that might even be useful to differentiate between patients with acute and relapsed brucellosis." (PMID 35071039, 2021). "The current study revealed that TRAF3IP2 and Th2-LCR lncRNA expression was particularly increased in the acute phase of brucellosis." (PMID 35071039, 2021). "TRAF3IP2 and Th2-LCR lncRNA might be good indicators of brucellosis during the acute phase, but the expression levels varied strongly among patients." (PMID 35071039, 2021).
cardiac hypertrophy (1 paper, 2019). "In particular, experiments in null mice evidence that the control of myocardial Lox expression depends on TRAF3 Interacting Protein 2 (TRAF3IP2), a redox-sensitive adaptor molecule and a decisive signaling intermediate in aldosterone/salt-induced cardiac hypertrophy and fibrosis." (PMID 31766500, 2019).
clear cell renal cell carcinoma (1 paper, 2022). "Since a lack of evidence has been found on the role of TRAF3IP2 in cancer, we first determined its clinical implication by comparing the expression of TRAF3IP2 in both NONO-TFE3 tRCC and clear cell renal cell carcinoma (ccRCC)." (PMID 35897085, 2022).
coronary artery stenosis (1 paper, 2025). "In this study, we used patients with mild stenosis as the control group and developed a multivariable diagnostic model incorporating TRAF3IP2 expression to predict severe coronary artery stenosis." (PMID 41189624, 2025).
coronary heart disease (1 paper, 2025). "The role of TRAF3IP2, a proinflammatory adaptor molecule, in the pathogenesis and prediction of coronary artery disease warrants systematic investigation." (PMID 41189624, 2025). "The purpose of this study was to explore the role of TRAF3IP2 in coronary artery disease and to develop and validate a nomogram for predicting the risk of coronary artery disease." (PMID 41189624, 2025).
fungal infection (1 paper, 2022). "However, this patient did not carry any variants in CARD9, IL17RA, L17RC, IL17F, STAT1, DOCK8, MALT1, or TRAF3IP2 genes that can explain the susceptibility to a severe and invasive fungal infection." (PMID 35091979, 2022).
hemorrhage (1 paper, 2020). Loss of blood from the vascular compartment to the exterior or into nonvascular body space as a result of rupture or severance of the blood vessels. "MiR-30a inhibits the transcriptional function of AP-1 by decreasing TRAF3IP2 expression, which finally can block arachnoid fibrosis and hydrocephalus formation after hemorrhage." (PMID 33335750, 2020).
Hydrocephalus (1 paper, 2020). Hydrocephalus is an active distension of the ventricular system of the brain resulting from inadequate passage of CSF from its point of production within the cerebral ventricles to its point of absorption into the systemic circulation. "For the first time, this study demonstrated the involvement of miR-30a in hydrocephalus development and confirmed that miR-30a affects TRAF3IP2/AP-1 signaling in thrombin-induced hydrocephalus formation." (PMID 33335750, 2020). "Therefore, after SAH, the activation of thrombin led to an incrassation in TGF-β1, which further induce the activation of the TRAF3IP2/AP-1 axis and finally lead to arachnoid fibrosis and hydrocephalus." (PMID 33335750, 2020).
Obesity (1 paper, 2021). Accumulation of substantial excess body fat. "In the present study, we found that obesity affected the expression patterns of βFaar and TRAF3IP2 in an opposite manner." (PMID 34183666, 2021). "Moreover, TRAF3IP2 was increased in the islets of HFD-fed and db/db mice (n = 5), and in the islets incubated with 0.5 mmol/l palmitate and pro-inflammatory cytokines, indicating a negative correlation between βFaar and TRAF3IP2 under conditions of obesity." (PMID 34183666, 2021).
overnutrition (1 paper, 2017). An imbalanced nutritional status resulting from excessive intake of nutrients. "Here we provide the first evidence of TRAF3IP2 upregulation in an overnutrition model and its inhibition by linagliptin." (PMID 28476142, 2017).
periodontal disease (1 paper, 2019). "Thirdly, rs17606253 (p-value 1.85 × 10− 6) harbored TRAF3IP2, a protein implicated in mucosal immunity and IL-17 signaling, and associated with a trait involving high levels of A. actinomycetemcomitans and a profile of aggressive periodontal disease." (PMID 31533690, 2019).
toxic epidermal necrolysis (1 paper, 2015). Toxic epidermal necrolysis (TEN) is an acute and severe skin disease with clinical and histological features characterized by the destruction and detachment of the skin epithelium and mucous membranes. "TRAF3IP2 genotypes and alleles distribution in Steven–Johnson Syndrome (SJS)/Toxic Epidermal Necrolysis (TEN) and controls." (PMID 25775161, 2015).